IL7 (interleukin 7)
Diseases named in the same sentence as IL7 in open-access papers (continued):
Sharing a sentence is not in itself a finding about the gene and the disease.
hypothyroidism (1 paper, 2023). Abnormally low levels of thyroid hormone. "By the IVW method, it was found that the level of IL-7 was associated with increased odds of developing hypothyroidism (IVW-OR: 1.042, 95% CI: 1.004-1.081, p = 0.028)." (PMID 38317717, 2023). "Conversely, when we treated hypothyroidism as an exposure factor, we detected a causal association between hypothyroidism and 13 inflammatory cytokines (IL-13, IL-16, IL-2rα, IL-6, IL-7, IL-9, G-CSF, SCGF-β, IP-10, MIG, MIP-1β, SDF-1α, and TNF-α)." (PMID 38317717, 2023). "Our results suggested that IL-7 and MIP-1β might cause hypothyroidism." (PMID 38317717, 2023). "Our study suggests that IL-7 and MIP-1β may play a role in the pathogenesis of hypothyroidism, and that hypothyroidism may induce a systemic inflammatory response involving multiple cytokines." (PMID 38317717, 2023).
IgA nephropathy (1 paper, 2023). "A previous study on RPTECs from patients with IgA nephropathy reported that upregulated IL-7 expression attenuated cellular fibrosis induced by transforming growth factor β l." (PMID 38137543, 2023).
immunotoxicity (1 paper, 2023). "Here, we show that the combination of engineered, tumor matrix-binding interleukin-7 (IL-7) and IL-12 achieves remarkable anticancer effects by activating complementary pathways without inducing any additive immunotoxicity." (PMID 38019919, 2023).
infertile (1 paper, 2012). "PBMCs from infertile patients without ASA produce significantly higher amounts of IL-7 after their cultivation of with whole sperm cells-antigen, as compared to either unstimulated or sperm cell lysate-stimulated PBMCs." (PMID 22952917, 2012). "When we compared cytokine spectra between both groups of infertile patients, we found that e.g. IL-13, IL-7, IL-17, and MIG are higher in patients without ASA, and IL-8 and MIP-1β are higher in patients with ASA." (PMID 22952917, 2012).
interstitial lung disease (1 paper, 2009). A diverse group of lung diseases that affect the lung parenchyma. "High IL-7 levels were characteristic of SSc-associated interstitial lung disease (ILD) and, in addition, when compared with ILD-negative SSc patients, ILD-positive SSc patients revealed higher IL-4, IL-6, IL-8, and CCL2 (MCP-1) BALF levels." (PMID 19615053, 2009).
intestinal cancer (1 paper, 2020). "Finally, we performed western blotting, immunohistochemistry, cell proliferation and cell apoptosis analysis to examine the expression of IL-7 in patients with intestinal cancer." (PMID 32381120, 2020). "Moreover, the mechanism by which IL-7 inhibited the progression of intestinal cancer required further research." (PMID 32381120, 2020). "However, our results show that IL-7 itself may inhibit the progression of intestinal cancer through the apoptotic pathway." (PMID 32381120, 2020).
invasive carcinoma (1 paper, 2020). A carcinoma that is not confined to the epithelium, and has spread to the surrounding stroma. "Downregulation of IL-7 is consistent with blunting of immune response, particularly T cell immunity at leading edge of invasive carcinoma." (PMID 32676161, 2020).
invasive ductal carcinoma (1 paper, 2022). "Interestingly, a lower value of IL-7 has been observed in the serum of patients with ILC compared to patients with invasive ductal carcinoma (IDC) and other histological subtypes, and the difference has been significant (P = 0.043)." (PMID 35794603, 2022).
invasive lobular carcinoma (1 paper, 2022). "Patients with invasive lobular carcinoma (ILC) seem to have a lower IL-7 serum level as compared to other histological subtypes, and the difference is significant (P = 0.043)." (PMID 35794603, 2022). "Patients with invasive lobular carcinoma (ILC) seem to have a lower IL-7 serum level compared to other histological subtypes, and the difference has been significant (P = 0.043)." (PMID 35794603, 2022).
iron deficiency (1 paper, 2025). "IL-1β (4.94 pg/mL for iron sufficiency, 8.09 pg/mL for iron deficiency, p = 0.029), and IL-7 were higher in iron deficiency patients (0.19 pg/mL for iron sufficiency, 0.39 pg/mL for iron deficiency, p = 0.014)." (PMID 39898042, 2025).
ischemia (1 paper, 2025). A hypoperfusion of the BLOOD through an organ or tissue caused by a PATHOLOGIC CONSTRICTION or obstruction of its BLOOD VESSELS, or an absence of BLOOD CIRCULATION. "Furthermore, IL-7 is also known as myokine, a protein synthesized and released from muscle fibers in response to physical exercise, and has been associated with tissue damage and ischemia." (PMID 40142185, 2025).
Jaundice (1 paper, 2022). Yellow pigmentation of the skin due to bilirubin, which in turn is the result of increased bilirubin concentration in the bloodstream. "Stratified analyses by disease severity uncovered that elevated plasma levels of IL-7, eotaxin, IP-10, and IL-13 were significantly associated with the presence of unfavorable outcomes including jaundice, fibrosis, and PH in BA patients." (PMID 35452452, 2022).
keloid (1 paper, 2023). An irregularly shaped, elevated mark on the skin caused by deposits of excessive amounts of collagen during wound healing. "A strong correlation between IL-7 and GLTP, GALC, ARSA, HEXB, and SUMF2 was found, suggesting that IL-7-based inflammatory factors may involve in keloid growth and development through associating with the GSL metabolism pathway." (PMID 37168863, 2023).
knee-osteoarthritis (1 paper, 2017). "Also, plasma levels of the anti-inflammatory cytokines IL-4, IL-7, IL-10, and IL-13 seem to increase after exercise in healthy subjects and IL-10 also in patients with knee-osteoarthritis." (PMID 28243900, 2017).
Legionella infection (1 paper, 2024). "Individuals with Legionella infection had higher IL-7 plasma levels compared to Legionella-negative individuals (0.50 [IQR 0.24–1.91] and 0.24 [IQR 0.24–0.25] pg/mL, respectively, p = 0.04)." (PMID 38392911, 2024).
Leukoencephalopathy (1 paper, 2018). This term describes abnormality of the white matter of the cerebrum resulting from damage to the myelin sheaths of nerve cells. "Patients with JC virus-induced progressive multi-focal leukoencephalopathy experienced clearing of viral levels in the cerebrospinal fluid, improved brain imaging, and resolution of clinical symptoms after treatment with IL-7." (PMID 29944697, 2018).
liver cirrhosis (1 paper, 2020). "Hence, IL-7 deficiency in patients with liver cirrhosis could be a factor of the well-known LPS tolerance and defective adaptive immunity in these patients." (PMID 33584648, 2020). "We therefore assessed whether IL-7 signaling can ameliorate LPS-tolerance in blood-derived monocytes and ascites-derived macrophages from patients with liver cirrhosis ex vivo." (PMID 33584648, 2020). "Furthermore, ISG-15 expression in PBMCs of patients with liver cirrhosis correlated significantly with IL-7-serum levels, suggesting an in vivo correlation between the activity of the IFN-system and IL-7 production." (PMID 33584648, 2020). "This notion is further supported by our result that liver cirrhosis patients including patients with ACLF display lower concentrations of IL-7 in serum compared to healthy controls, a scenario in which therapeutic application of IL-7 could be particularly relevant." (PMID 33584648, 2020). "Indeed, we could observe a trend of an IL-7-mediated blunted LPS tolerance in monocytes and ascites macrophages of patients with liver cirrhosis ex vivo." (PMID 33584648, 2020). "Finally, we show that patients with liver cirrhosis have reduced concentrations of IL-7 in serum in comparison to healthy controls, a factor which may contribute to LPS tolerance, a cardinal feature of liver cirrhosis-associated immunodysfunction." (PMID 33584648, 2020). "Although we can only speculate about the mechanism of reduced IL-7 serum concentrations in patients with liver cirrhosis, an explanation could be the significantly reduced liver mass of these patients with the consequence of a lower hepatic cell pool being able to secrete IL-7 in response to IFN." (PMID 33584648, 2020). "From a clinical point of view, our data suggest that IL-7 (or inhibition GSK3 in macrophages) might be of value to prevent and treat infections in liver cirrhosis patients and thereby to prevent and ameliorate the development of ACLF and death." (PMID 33584648, 2020). "However, liver cirrhosis patients with or without ACLF had significantly lower concentrations of IL-7 in serum compared to healthy controls, which might contribute to LPS-tolerance in these patients." (PMID 33584648, 2020).
lymphocytic thyroiditis (1 paper, 2014). "The high expression of IL-7 may be used in differentiating thyroid lymphoma from lymphocytic thyroiditis." (PMID 25364417, 2014).
malignant pleural mesothelioma (1 paper, 2022). A malignant neoplasm that arises from mesothelial cells in the pleura and shows a diffuse growth pattern. "In this study, we aimed at evaluating the IL‐7R/IL‐7 pathway in malignant pleural mesothelioma (MPM)." (PMID 36054746, 2022).
mastitis (1 paper, 2025). Inflammation of breast tissue during lactation or postpartum due to an obstructed duct or infection. "DEGS such as IL10, CCL5, IL1B, OSM, TNFRSF1B, IL7, and CCR3, among others, implicated in these pathways, may play a crucial role in the development of subclinical mastitis in Bactrian camels, though further analysis is needed to explore their potential functions." (PMID 40005880, 2025).
mastocytoma (1 paper, 2022). A localized tumor composed of sheets of mast cells without atypia. "IL-7– and CCL19-expressing (7 × 19) CAR T cells showed a stronger therapeutic effect against mouse mastocytoma with increased endogenous DC and T-cell infiltration." (PMID 36059449, 2022).
meningitis (1 paper, 2020). A disorder characterized by acute inflammation of the meninges of the brain and/or spinal cord. "As expected, in the PFC, we observed increased levels of pro-inflammatory cytokines such as IL1-α, IL1-β, IL-6, IL-17, TNF-α, and INF-γ (P < 0.05) and decreased levels of IL-7, IL-10, and IL-13 (P < 0.05) in the 24-h meningitis group." (PMID 31901235, 2020).
mesothelioma (1 paper, 2022). A usually malignant and aggressive neoplasm of the mesothelium which is often associated with exposure to asbestos. "The objective of this study was to evaluate the IL‐7/IL‐7R pathway in mesothelioma using a collection of samples from patients." (PMID 36054746, 2022). "Because soluble mesothelin‐related protein (SMRP) is currently the best diagnostic biomarker for mesothelioma, we also measured SMRP concentration in PEs by ELISA and found a significant but weak correlation between IL‐7 and SMRP levels in MPM (Spearman r = 0.279; P = 0.0176)." (PMID 36054746, 2022).
metastatic prostate carcinoma (1 paper, 2019). A carcinoma that arises from the prostate gland and has spread to other anatomic sites. "Thus, we investigated the role of IL-7 in tumor invasiveness using metastatic prostate cancer PC-3 cell line derivatives, and assessed the potential of IL-7 as a clinical target using a Janus kinase (JAK) inhibitor and an IL-7-blocking antibody." (PMID 31061414, 2019).
microcephaly (1 paper, 2021). A congenital or acquired developmental disorder in which the circumference of the head is smaller than normal for the person's age and sex. "In the canonical coefficient analysis between controls and those exposed to ZIKV without microcephaly, we found that IL-1β, IL-3, IL-4, IL-7 and EOTAXIN (CCL11) were the top CSF markers in our model." (PMID 33875756, 2021). "When cases (with or without microcephaly) were compared with controls, IL-1α, IL-7, IP10 (CXCL10), and GCSF were significantly higher among controls." (PMID 33875756, 2021).
morbid obesity (1 paper, 2023). An excess of body weight, normally defined as an individual with a body mass index greater than 35 or a body weight greater than one hundred percent of ideal body weight. "In this context, it is important to mention that IL-7 levels were shown to be increased in patients with morbid obesity." (PMID 37266430, 2023).
myelofibrosis (1 paper, 2025). A partial or complete replacement of the bone marrow stroma by fibrous tissue. "We identified a set of inflammatory cytokines, including IL-1alpha, IL-4, IL-6, IL-7, IL-9, IL-15 and TNF-alpha, which are elevated in the serum of JAK2V617F mice, similar to the alterations in circulating cytokines observed in patients with myelofibrosis." (PMID 40386398, 2025).
myeloid leukemia (1 paper, 2023). A clonal proliferation of myeloid cells and their precursors in the bone marrow, peripheral blood, and spleen. "Overall, these studies collectively demonstrate that acute lymphoid and myeloid leukemias turn off lymphopoiesis by expressing LTβR ligands and downregulating IL7 production." (PMID 36912771, 2023).
myocarditis (1 paper, 2021). Myocarditis is a condition that is characterized by inflammation of the heart muscle (myocardium). "For instance, considering that opioid use exacerbates the up regulation of IL-6, it may worsen the inflammation and consequent cardiovascular outcomes (e.g., myocarditis, plaque rupture) related to the cytokine storm of L-6, IL-7, and IL-22 induced by the viral invasion of SARS-CoV-2." (PMID 34803676, 2021).
Ovarian cyst (1 paper, 2019). The presence of one or more cysts of the ovary. "Three proteins (6Ckine, Lipocalin-2, IL-7), on the other hand, were differentially expressed between ovarian cyst patients and healthy controls." (PMID 31333337, 2019).
ovarian tumours (1 paper, 2018). "In this study we proposed a new mathematical model that described the interactions between tumour and immune cells, and the secretion of tumour biomarkers (CA-125) and immune biomarkers (IL-7) that could be both used to predict the presence of ovarian tumours." (PMID 29554938, 2018).
pancreatic ductal adenocarcinoma (1 paper, 2022). An infiltrating adenocarcinoma that arises from the epithelial cells of the pancreas. "We thus tested the plasma of patients with pancreatic ductal adenocarcinoma (PDAC) for the presence of inhibitory PLA2G1B activity that impairs the CD4 T-cell response to IL-7." (PMID 35392090, 2022). "Notably, the bacteria Porphyromonas gingivalis, which is associated with pancreatic ductal adenocarcinoma (PDAC), encodes such a cofactor protein and increased PLA2G1B activity in PDAC patient plasma inhibits the CD4 response to IL-7." (PMID 35392090, 2022).
pancreatitis (1 paper, 2025). Inflammation of the pancreas. "In pancreatitis, IL-7 expression levels increase over time, peaking within 72 hours of the acute phase, indicating its involvement in the inflammatory response of pancreatitis." (PMID 39958351, 2025). "Future research could further explore the mechanisms of IL-7’s interaction with T cells in pancreatitis." (PMID 39958351, 2025).
Parkinson disease (1 paper, 2026). A progressive degenerative disorder of the central nervous system characterized by loss of dopamine producing neurons in the substantia nigra and the presence of Lewy bodies in the substantia nigra and locus coeruleus. "(ii) Metabolic pathways, including the adipokine (chemokine-like protein TAFA-5), were associated with Parkinson's disease diagnosis, and (iii) inflammatory pathways (interleukin-7) were associated with Parkinson's disease diagnosis." (PMID 41783831, 2026).
pemphigus (1 paper, 2023). Pemphigus is a group of rare autoimmune diseases that cause blistering of the skin and mucous membranes (mouth, nose, throat, eyes, and genitals).This conditioncan occur at any age, but often strikes people in middle or older age. "It is thus intriguing that the increase of Flavonifractor and positive correlation between Flavonifractor and circulating inflammatory markers (C5a, IL-6, IL-8, IL-7, IL-1β and IL-21) were reported in pemphigus vulgaris, a subgroup of pemphigus." (PMID 38022583, 2023).
plasmacytoma (1 paper, 2012). Plasmacytoma is a localized mass of neoplastic monoclonal plasma cells that represents approximately 5% of all plasma cell neoplasms. "We retrovirally transduced murine pro-B cell line 38B9, murine pre-B cell line 3-1, murine plasmacytoma cell line S194, and Il-7 cultured primary bone marrow B cells with MigR1-FlagYY1 or empty MigR1 vector." (PMID 22292011, 2012). "In contrast, the percentage of MigR1-YY1 transduced GFP positive cells declined dramatically in murine pro-B, pre-B, plasmacytoma, and Il-7 cultured bone marrow B cells, indicating growth arrest and/or cell death." (PMID 22292011, 2012).
prediabetes (1 paper, 2023). "However, HbA1c was found to be positively correlated with IL-7 in overweight/obese young subjects with prediabetes." (PMID 35801423, 2023).
progressive multifocal leukoencephalopathy (1 paper, 2021). Progressive multifocal leukoencephalopathy (PML) is a neurological disorder that damages the myelin that covers and protects nerves in the white matter of the brain. "For example, a case report of a patient with progressive multifocal leukoencephalopathy (PML) showed that IL-7 decreased circulating John Cunningham (JC) virus, rapidly increased lymphocytes, and contributed to disease resolution." (PMID 34925323, 2021).
pulpitis (1 paper, 2021). Inflammation of the dental pulp. "On the other hand, IL-7 and IL-13 levels were significantly higher in normal pulp tissue when compared to reversible and irreversible pulpitis." (PMID 34299403, 2021).
rectal cancer (1 paper, 2017). A primary or metastatic malignant neoplasm that affects the rectum. "We observed IL-7 to be significantly more elevated in right than left or rectal cancers, and the association was not mediated by differences in stage or metastatic lymph node distribution." (PMID 27866242, 2017).
relapsed (1 paper, 2019). "Interleukin 7 (IL-7) and its receptor IL-7Rα promote T-ALL development and mutational activation of IL-7Rα associates with very high risk in relapsed disease." (PMID 30850736, 2019).
relapsing-remitting multiple sclerosis (1 paper, 2024). The most common clinical variant of multiple sclerosis, characterized by recurrent acute exacerbations of neurologic dysfunction followed by partial or complete recovery. "Our study showed that the levels of IL-7 in the cerebrospinal fluid of people with newly diagnosed relapsing-remitting multiple sclerosis (RRSM) were lower than in healthy controls." (PMID 39000506, 2024).
sacroiliitis (1 paper, 2023). "Similarly, interleukin-7 was suggested as another inflammatory marker for patients with sacroiliitis." (PMID 37871023, 2023).
Salmonella Infections (1 paper, 2017). Infections with bacteria of the genus SALMONELLA. "In accordance with prior studies, our data demonstrate that probiotic LGG attenuated the upregulation of intestinal IL-7 and IL-7Rα expression induced by Salmonella infection, thereby contributing to the amelioration of intestinal inflammation." (PMID 28770173, 2017).
schistosomiasis (1 paper, 2018). An infectious disease caused by parasitic trematodes of the genus Schistosoma that colonize human blood vessels and release eggs that can cause granulomatous reactions leading to acute (swimmer's itch or acute schistosomiasis syndrome) or chronic disease. "Our results suggest that induction of macrophage autophagy through IL‐7 blockade may be a potential therapeutic strategy against tissue immunopathology in diseases including schistosomiasis." (PMID 29566311, 2018).